S1PR2 (sphingosine-1-phosphate receptor 2)
Description:
Receptor for the lysosphingolipid sphingosine 1-phosphate (S1P). S1P is a bioactive lysophospholipid that elicits diverse physiological effects on most types of cells and tissues. When expressed in rat HTC4 hepatoma cells, is capable of mediating S1P-induced cell proliferation and suppression of apoptosis. Receptor for the chemokine-like protein FAM19A5. Mediates the inhibitory effect of FAM19A5 on vascular smooth muscle cell proliferation and migration (By similarity). In lymphoid follicles, couples the binding of S1P to the activation of GNA13 and downstream inhibition of AKT activation leading to suppression of germinal center (GC) B cell growth and migration outside the GC niche.
Synonyms: S1P2; EDG5; Gpcr13; H218; AGR16; DFNB68; EDG-5; LPB2
Tractability: Small molecule: an approved drug acts on it; a structure with a bound ligand is known; a high-quality ligand is known; it belongs to a druggable protein family. Antibody: UniProt places it where antibodies can reach, with high confidence; its Gene Ontology location is reachable by antibodies, with high confidence; UniProt predicts a signal peptide or a membrane-spanning region. PROTAC: a small molecule that binds it is known.
Target class: EDG receptor; Family A G protein-coupled receptor; Lipid-like ligand receptor (family A GPCR); Membrane receptor; Small molecule receptor (family A GPCR)
Chemical probes: CHEMBL3401388, ML031
Gene: Protein-coding gene on chromosome 19 (10,221,433 to 10,231,331, reverse strand). Ensembl gene ENSG00000267534.
Subcellular location: Cell membrane
Subcellular location (Human Protein Atlas): Golgi apparatus; Nuclear speckles
Pathways (Reactome):
Signal Transduction: G alpha (i) signalling events; Lysosphingolipid and LPA receptors
Gene Ontology:
Molecular function: G protein-coupled peptide receptor activity; G protein-coupled receptor binding; integrin binding; protein binding; sphingosine-1-phosphate receptor activity; G protein-coupled receptor activity; lipid binding
Biological process: actin cytoskeleton organization; filopodium assembly; G protein-coupled receptor signaling pathway; positive regulation of establishment of endothelial barrier; sphingosine-1-phosphate receptor signaling pathway; adenylate cyclase-activating G protein-coupled receptor signaling pathway; positive regulation of cell population proliferation; regulation of postsynapse assembly
Cellular component: plasma membrane; cytoplasm; glutamatergic synapse; membrane; presynapse
Genetic constraint (gnomAD): Loss-of-function variants: 10 observed, 20.35 expected, observed/expected ratio (o/e) 0.49, 90% interval 0.3 to 0.83. The upper end of that interval is the gene's LOEUF score, 0.83, which puts it in group 3 of 6, group 1 being the genes least tolerant of losing a copy. Missense variants: 361 observed, 497.52 expected, observed/expected ratio (o/e) 0.73, 90% interval 0.67 to 0.79. Synonymous variants: 224 observed, 239.15 expected, observed/expected ratio (o/e) 0.94, 90% interval 0.84 to 1.05.
Gene-disease validity (ClinGen):
ClinGen rates the evidence that S1PR2 causes each of these diseases.
nonsyndromic genetic hearing loss (autosomal recessive): Strong.
Homologues: Orthologues: chimpanzee S1PR2 (99% identical), macaque S1PR2 (99% identical), rabbit S1PR2 (92% identical), mouse S1pr2 (91% identical), rat S1pr2 (90% identical), dog S1PR2 (90% identical), guinea pig S1PR2 (89% identical), pig S1PR2 (89% identical), tropical clawed frog s1pr2 (61% identical), zebrafish s1pr2 (57% identical). Paralogues in human: S1PR1 (46% identical), S1PR5 (45% identical), S1PR3 (42% identical), S1PR4 (36% identical), LPAR2 (32% identical), LPAR3 (30% identical), LPAR1 (29% identical), GPR6 (25% identical), CNR1 (24% identical), GPR12 (24% identical), MC3R (24% identical), GPR3 (23% identical), and 6 more.
Diseases named in the same sentence as S1PR2 in open-access papers:
S1PR2 is named in the same sentence as 199 diseases in open-access papers, as found by Europe PMC text mining. Sharing a sentence is not in itself a finding about the gene and the disease. The quoted sentences say what the papers report.
liver fibrosis (28 papers, 2015 to 2025). "S1PR2 deficiency decreased macrophage pyroptosis and improved survival in E. coli sepsis 30 and also significantly reduced inflammation and liver fibrosis." (PMID 39664579, 2024). "In the carbon tetrachloride-induced model of hepatic fibrosis, S1PR2-deficient mice experienced decreased fibrosis." (PMID 28322247, 2017). "S1P activates HSCs via S1PR2, promoting liver fibrosis, and stimulates proliferation of the hepatocytes via S1PR1." (PMID 40647361, 2025). "Experiments using mice with conditional knockout of SphK and S1PR2 are also required to confirm the involvement of S1P from LSECs in liver fibrosis." (PMID 38753743, 2024). "According to previous literature, the activation of S1PR2 was found to promote inflammation and liver fibrosis through the NLRP3 pathway, as well as modulate neutrophil exocytic reticulum." (PMID 38250717, 2024). "For instance, the role of S1PR2 in promoting inflammation initiation and liver fibrosis development through the NLRP3 pathway has been demonstrated." (PMID 38250717, 2024). "Mice treated with the S1PR2 inhibitor JTE013 or S1PR2KO showed decreased liver fibrosis, as demonstrated by reduced Sirius Red staining, hydroxyproline content, and αSMA expression." (PMID 38753743, 2024). "Blockage of S1PR2/ZBP1/p-MLKL axis caused the decrease of necroptosis, and importantly, the attenuation of liver fibrosis." (PMID 36859525, 2023). "In BDL-induced liver fibrosis, selectively knocking down of macrophage S1pr2, Zbp1 or Mlkl blocked S1PR2/ZBP1/p-MLKL axis." (PMID 36859525, 2023). "S1PR2 deficiency dramatically decreases bile duct ligation-induced bile duct cell proliferation and bile stasis damage, as evidenced by a significant decrease in inflammation and hepatic fibrosis in S1PR2 knockout mice." (PMID 38057297, 2023). "S1PR2 inhibition mitigated liver fibrosis development and S1PR2 blockage has been shown to accelerate HCC progression in mice." (PMID 36386790, 2022). "Our previous studies reported that increased primary conjugated bile acid is responsible for cholestatic liver injury and liver fibrosis by activating sphingosine-1 phosphate receptor 2 and lncRNAH19." (PMID 33494295, 2021). "Our previous study had reported that S1pr2 and SphK2 played an important role in promoting liver fibrosis." (PMID 33138822, 2020). "Knockout of the S1PR2 in this model protects mice from the development of fibrosis, suggesting a crucial role of this receptor subtype in the development of liver fibrosis." (PMID 29510489, 2018). "Our results provide new compelling information on the role of S1PR2/3 in liver injury and opens new perspectives for the pharmacological treatment of hepatic fibrosis." (PMID 26324256, 2015). "S1P stimulated the activation of HSCs and liver fibrosis via S1PR2-mediated signaling." (PMID 38753743, 2024). "S1P level is increased in MASH livers and contributes to liver fibrosis via S1PR2." (PMID 38753743, 2024). "In conclusion, GDCA/S1PR2/ZBP1/p-MLKL mediated macrophage necroptosis plays vital role in the pathogenesis of BA liver fibrosis, and targeting this process may represent a potential therapeutic strategy for BA." (PMID 36859525, 2023). "Moreover, JTE-013 and S1PR2 knockdown significantly reduced the proliferation of cholangiocytes, cholestatic injury, inflammation, and liver fibrosis by acting on ERK1/protein kinase B." (PMID 37895915, 2023). "Increased hepatic/serum conjugated primary bile acids may be an important factor in cholestatic liver injury and liver fibrosis by activating S1PR2 and H19." (PMID 36224648, 2022). "Furthermore, several studies are reporting that activating S1PR2 promotes hepatic fibrosis, portal hypertension, BECs proliferation and liver injury in the animal models of cholestasis." (PMID 36339341, 2022). "Conversely, the knockdown of S1pr2 in mice reduces liver fibrosis induced by bile duct ligation." (PMID 36189347, 2022).
liver fibrosis (continued). "TCA-induced activation of S1PR2 is involved in cholangiocyte proliferation and hepatic fibrosis." (PMID 34831031, 2021). "The expression of S1PR2 is correlated to hepatic fibrosis under cholestatic conditions." (PMID 34831031, 2021). "For these reasons, we explored the role of S1PR2/3 in fatty liver injury and asked whether S1PR2/3 could be effective therapeutic targets for inhibiting inflammation and alleviating liver fibrosis in vivo." (PMID 31546702, 2019). "In analogy, the S1PR2 antagonist JTE-013 is able to diminish liver fibrosis." (PMID 29510489, 2018). "Finally, we analyzed the effects of S1PR2 and S1PR3 antagonists on the underlying liver fibrosis process." (PMID 26324256, 2015). "Additionally, TCA may promote liver fibrosis by binding to S1PR2 and activating the ERK1/2-sphingosine kinase 2 signaling pathway via the upregulation of genes involved in cell proliferation and metabolism and the induction of NF-κB expression." (PMID 36189347, 2022). "More importantly, selective knockdown of S1pr2, Zbp1 or Mlkl in macrophage decreased ZBP1/p-MLKL-mediated necroptosis, and further attenuated liver fibrosis in BDL-induced cholestatic liver injury." (PMID 36859525, 2023). "Selective blockage of S1PR2/ZBP1/p-MLKL axis in macrophage attenuated necroptosis and liver fibrosis in BDL mice." (PMID 36859525, 2023). "The inhibition of S1PR2 or its knockout in mice suppressed liver fibrosis without reducing steatosis or hepatocellular damage." (PMID 38753743, 2024). "In conclusion, all these results showed that blockage of GDCA/S1PR2/ZBP1/p-MLKL axis-mediated necroptosis, which was an important player of cholestatic liver fibrosis, could be potential target of BA liver fibrosis." (PMID 36859525, 2023). "Our results help in better understanding the role of GDCA/S1PR2/ZBP1/p-MLKL mediated macrophage necroptosis in cholestatic liver diseases, and might provide novel therapeutic strategies to attenuate BA liver fibrosis." (PMID 36859525, 2023). "In conclusion, S1P/S1PR2/3 system mediates BMM motility by PTX-PI3K-Rac1 signaling pathway, which provides new compelling information on the role of S1P/S1PR in liver injury and opens new perspectives for the pharmacological treatment of hepatic fibrosis." (PMID 26324256, 2015).
breast carcinoma (21 papers, 2016 to 2025). "In fact, elevated level of cytoplasmic S1PR1 and nuclear S1PR2/S1PR3 expression are associated with breast cancer survival." (PMID 31861214, 2019). "Breast cancer cells secrete exosomes containing S1PR2 that if processed to a shorter form that activates ERK1/2 signaling and proliferation in recipient fibroblasts." (PMID 32957712, 2020). "Ohotski et al36 also indicated that nuclear localization of sphingosine kinase 1 and S1PR2 played an important role in breast cancer prognosis." (PMID 29923327, 2018). "An additional study showed that S1PR2 from breast cancer stem cells activated fibroblasts." (PMID 33758708, 2021). "Indeed, S1PR5 has been found in centrosomes and S1PR2 translocates to the nucleus in breast cancer cells." (PMID 31861214, 2019). "In breast cancer cell lines, however, the use of tamoxifen and medroxyprogesterone result in the downregulation of S1PR3 and stimulation of S1PR2 with activation of autophagy of the breast cancer cells towards death, again demonstrating the detrimental role of S1P pathway activation in cancer." (PMID 29147072, 2017). "In vitro, S1P increased p21 expression in Leydig cells by S1PR2, which is different from a previous report that S1P upregulates p21 expression independently of its cell surface receptors in human MCF-7 breast cancer cells." (PMID 34083520, 2021). "Compared with normal breast epithelium cells, RFX5, VEGFA were upregulated in breast cancer cells, IKZF2, NAB1, S100B were downregulated in breast cancer cells while F2R, S1PR2 showed no significance." (PMID 40520263, 2025). "In addition, F2R, S1PR2 showed no significance between normal breast epithelium cells and breast cancer cells." (PMID 40520263, 2025). "Interestingly, we detected S1PR2 expression in the membrane, cytoplasm and nucleus of tumour cells and it has been shown recently that S1PR4 functions to prevent nuclear accumulation of S1PR2 to enhance the growth of ER negative breast cancer cells." (PMID 27160553, 2016). "However, the study did not reveal S1PR2, S1PR4 mRNA, or protein levels in MDA-MB-453 breast cancer cells treated with JTE013." (PMID 34769490, 2021).
atherosclerosis (19 papers, 2015 to 2025). A disease characterized by the build-up of fatty material and calcium deposition in the arterial wall resulting in partial or complete occlusion of the arterial lumen. "It is worthy of note that S1PR2 signaling has been confirmed to play a pathogenic role in a range of inflammation-related diseases, interestingly, atherosclerosis, acute vascular inflammation, vasculitis, and cerebral ischemia/reperfusion injury are included." (PMID 34977175, 2021). "In addition, genetic deletion of either S1pr2 or S1pr3 diminished atherosclerosis associated with suppression of macrophage infiltration in a murine model, indicating that S1PR2 and S1PR3 facilitate atherosclerosis." (PMID 31797978, 2019). "Additionally, S1PR2 has been also implicated in modulating proinflammatory cytokine production in inflammatory bone loss diseases as well as atherosclerosis." (PMID 29854830, 2018). "The seed node is S1PR2, which plays a vital role in atherosclerosis and can be used as a novel therapeutic target for atherosclerosis." (PMID 34433871, 2021). "In mouse models of atherosclerosis, genetic knockout (KO) studies showed that S1PR2 and S1PR3 facilitate atherosclerosis, whereas pharmacological stimulation of S1PR1diminishes atherosclerosis." (PMID 31797978, 2019). "Concerning macrophages, S1PR2 retains them in atherosclerotic plaques and regulates their inflammatory cytokine secretion to promote atherosclerosis." (PMID 31379883, 2019). "In mouse models of atherosclerosis, S1PR2 signaling in activated macrophages was shown to promote production of proinflammatory cytokines (e.g., IL-1β, IL-18), and S1PR2 may retain macrophages in atherosclerotic plaques." (PMID 39854311, 2025). "Therefore, the authors suggested that S1PR2 signaling regulates macrophage infiltration and inflammatory cytokine secretion, thereby promoting atherosclerosis." (PMID 36119733, 2022). "In addition, S1PR2 signaling has been widely recognized as a driver of multiple inflammatory diseases, such as atherosclerosis, acute vascular inflammation, cerebral ischemia/reperfusion injury, rheumatoid arthritis, and hepatic inflammation." (PMID 34977175, 2021). "Activation of S1PR2 leads to decreased proliferation and migration of smooth muscle cells, which is considered to be involved in accelerating the pathological processes in the development of cardiovascular diseases, such as atherosclerosis." (PMID 32803879, 2020). "In addition, Skoura and colleagues proved that S1PR2 expressed in macrophages of atherosclerotic plaque regulates inflammatory cytokine secretion (IL-1β, IL-18) and promotes atherosclerosis." (PMID 27965665, 2016). "Blocking S1PR2 signaling might be a novel therapeutic strategy to the HFD-related inflammatory diseases such as atherosclerosis and IBD." (PMID 27965665, 2016). "S1PR2 expression also induces increased macrophage accumulation in atherosclerosis plaque and promotion of inflammation in mice, and its increased expression could thus also contribute to the macrophage accumulation that has been reported in current smokers with or without COPD." (PMID 26485657, 2015). "In summary, gut microbiota-derived secondary BAs play important roles in the development of atherosclerosis through the modulation of various BA receptors such as FXR, PXR, TGR5, VDR, and S1PR2." (PMID 30319417, 2018). "Although many details on the role of S1P and macrophages during atherosclerosis still need to be discovered, a gross simplification would favor anti-atherosclerotic actions of S1PR1 and S1PR3, while pro-atherosclerotic functions of S1PR2 may dominate." (PMID 31379883, 2019).